HMGB1 (high mobility group box 1)
Diseases named in the same sentence as HMGB1 in open-access papers (continued):
Sharing a sentence is not in itself a finding about the gene and the disease.
Cerebral ischemia (continued). "Previous report found, anti-HMGB1 mAb effectively reduced brain ischemia by efficient clearance of HMGB1 and inhibiting edema, ameliorates spontaneous arthritis model, prevent joint destruction, and repair cardiac pathological changes in experimental autoimmune myocarditis by suppress Th-17 cell." (PMID 36310854, 2022). "Clinical studies have shown that elevated HMGB1 serum levels could be detected in patients suffering from myocardial or cerebral ischemia." (PMID 34776788, 2021). "Furthermore, HMGB1 has been shown to activate TLR4 to induce MMP-9 upregulation following cerebral ischemia." (PMID 33487119, 2021). "For instance, notoginsenoside R1 protects the injury induced by hypoxia and re-oxygen deprivation via upregulation of miR-132 in H9c2 cells, and demedetomidine modulates miR-205-5p via targeting cerebral ischemia/reperfusion HMGB1 for repression of inflammatory response and oxidative stress." (PMID 34709114, 2021). "Moreover, high-mobility group box 1 (HMGB1) is released resulting in TLR4-dependent MMP-9 upregulation in the brain following cerebral ischemia in mice." (PMID 33487119, 2021). "Neuroinflammation that is stimulated by DAMPs (e.g., HMGB1 and Prxs) after brain ischemia was shown to be negatively regulated by MSR1, which conferred potent neuroprotection within a 24-h therapeutic time window in mice that were subjected to transient middle cerebral artery occlusion (tMCAO)." (PMID 34162400, 2021). "In the progression of cerebral ischemia, the passive release and active secretion of HMGB1 are not completely independent but are mutually causal." (PMID 33384585, 2020). "Moreover, we discuss the possible mechanisms of the role of HMGB1 in cerebral ischemia and the key approaches to inhibit HMGB1 as a potential novel molecular target in cerebral ischemia." (PMID 33384585, 2020). "However, information about the characteristics of HMGB1 after cerebral ischemia is very limited in the immature brain." (PMID 33384585, 2020). "Based on previous preclinical and clinical studies, HMGB1 may be thought of as a hopeful non-invasive biomarker of cerebral ischemia." (PMID 33384585, 2020). "In addition, HMGB1 is also actively secreted by microglia, macrophages, and neutrophils, and recent studies have explored the role of HMGB1 produced by these cells in cerebral ischemia." (PMID 33384585, 2020). "These investigations indicate that HMGB1 modulation may be a therapeutic target for brain ischemia and post-ischemic inflammation." (PMID 33287126, 2020). "Actually, numerous studies have demonstrated that berberine could inhibit HMGB1/Nf-κB pathway in a variety of diseases models, such as brain ischemia, endotoxic shock, and acetaminophen hepatotoxicity." (PMID 32754040, 2020). "Furthermore, cytokine-inducing disulfide HMGB1 was discovered in mouse serum after 24 h of cerebral ischemia." (PMID 31001089, 2019). "However, it is reported that all-thiol HMGB1 is oxidized, leading to the formation of disulfide state at the three cysteine residues, when it is released into the circulation after cerebral ischemia." (PMID 31001089, 2019). "We investigated whether UA reduced inflammatory cytokine production to protect the brain from cerebral ischemia and reperfusion injury possibly though the HMGB1/TLR4/NFκB signaling pathway." (PMID 29867706, 2018). "TLR4 is expressed primarily in microglia and astrocyte in the central nervous system and can be activated by DAMPs (such as HMGB1) to induce downstream signals that lead to cytokine production and thus initiation of an inflammatory response after cerebral ischemia and reperfusion injury." (PMID 29867706, 2018). "Brain ischemia/reperfusion can induce HMGB1 translocation and release." (PMID 30139371, 2018).
Cerebral ischemia (continued). "Blood–brain barrier (BBB) breakdown and inflammatory responses are the major causes of tissue-type plasminogen activator (tPA)-induced hemorrhagic transformation (HT), while high-mobility group box 1 (HMGB1) exacerbates inflammatory damage to BBB during the process of brain ischemia/reperfusion." (PMID 30139371, 2018). "Also, HMGB1 mediates cross-talk between reactive astrocytes and EPCs to promote functional recovery following focal cerebral ischemia." (PMID 29054968, 2017). "They therefore proposed that down-regulation of HMGB1-induced NF-κB activation pathway might be a potential mechanism of atorvastatin’s neuroprotection in cerebral ischemia." (PMID 29054968, 2017). "HMGB1 relation with NF-κB activation pathway may be one of Tan II A’s effective therapeutic targets for cerebral ischemia." (PMID 29054968, 2017). "It has been proven that HMGB1 has essential roles for microglial activation minutes after cerebral ischemia and may still be detected in microglia up to days after cerebral ischemia." (PMID 29054968, 2017). "HDAC5 and HDAC4 were markedly reduced in both cerebral ischemia/reperfusion injury and OGD model, and NADPH oxidase-reduced HDAC4 and HDAC5 accelerates cerebral ischemia injury via increasing the expression and release of high mobility group box-1 protein (HMGB1)." (PMID 27330844, 2016). "Moreover, the increase of HMGB1 expression after cerebral ischemia activated inflammatory pathways via RAGE and TLRs, leading to brain damage." (PMID 27563308, 2016). "Increased levels of HMGB-1 have been found following myocardial ischemia, in cerebral ischemia subjects and in chronic kidney disease patients, where this elevation correlates well with inflammatory markers in the synovial fluid as well as with a reduction in glomerular filtrate." (PMID 21507210, 2011). "In patients who suffer cerebral ischemia, HMGB1 levels in the serum are increased." (PMID 21040547, 2010). "A role for HMGB1 in cerebral ischemia is indicated by the observation that downregulation of HMGB1 by RNA interference or by using neutralizing antibodies leads to reduced infarct volume and suppression of microglial activation and neuroinflammation in rat and mouse MCAo models." (PMID 21040547, 2010). "Similar rapid, active release HMGB1 has also been reported in experimental brain ischemia." (PMID 20565784, 2010). "Moreover, inhibition of HMGB1 can intercept ferroptosis and alleviate cerebral ischemia." (PMID 39967676, 2025). "Notoginseng leaf triterpenes reduced HMGB1 expression, inhibited activation of MAPKs and NF-κB to suppress neuroinflammation, and suppressed microglia activation in the hippocampus and cortex, thereby facilitating cerebral ischemia–reperfusion-induced neuropathological changes." (PMID 38740617, 2025). "In the present study, we tested the hypothesis that the microglial MPO-containing exosomes increase adjacent neuronal HOCl production and mediate disulfide HMGB1 translocation, subsequently aggravating the ischemic brain injury and neurological deficits in cerebral ischemia–reperfusion (I/R) injury." (PMID 38515139, 2024). "However, the precise mechanism through which EA exerts its neuroprotective effects in cerebral ischemia, particularly its modulation of the HMGB1/RAGE signaling pathway, remains unclear." (PMID 37829255, 2023). "The HMGB1/RAGE pathway could be activated after cerebral ischemia." (PMID 37829255, 2023). "Therefore, our findings suggest that acupoint EA may mitigate neurological impairment resulting from cerebral ischemia through modulation of the HMGB1/RAGE pathway." (PMID 37829255, 2023). "Interestingly, a fully reduced form of HMGB1 has been found in the brain and serum early after experimental cerebral ischemia; however, the oxidized disulfide form of HMGB1 with a cytokine-inducing capability dominates after 24 h of middle cerebral artery occlusion (MCAO)." (PMID 36232519, 2022).
Cerebral ischemia (continued). "Therefore, systemic HMGB1 is a potent proinflammatory mediator of cerebral ischemia." (PMID 35243897, 2022). "Moreover, HMGB1 has been shown to be associated with larger infarct sizes and BBB disruption, as all of these changes were improved upon antagonizing HMGB1 after experimental cerebral ischemia." (PMID 36232519, 2022). "Therefore, inhibition of elevation of HMGB1 and upregulation of M1 macrophages/microglia may represent a novel therapeutic target in the neuroinflammatory stage after cerebral ischemia." (PMID 35243897, 2022). "Therefore, Hp may prevent aggravation by HMGB1 after cerebral ischemia and promote tissue repair by M2 macrophages/microglia." (PMID 35243897, 2022). "However, it is still unclear whether HMGB1 is involved in the neuroplasticity mechanism after cerebral ischemia in adults and whether it is related to the recovery after perinatal ischemic hypoxia." (PMID 33384585, 2020). "Thus our findings could be extended to several other types of acute brain injury, most notably to TBI and brain ischemia where HMGB-1 has been shown to play a major role." (PMID 31507379, 2019). "Moreover, in a mouse model of brain ischemia–reperfusion injury based on middle cerebral arterial occlusion, C5b-9 complexes were deposited on vessels where HMGB1 was accumulated, an effect that was suppressed upon HMGB1 neutralization." (PMID 29696019, 2018). "NADPH oxidase activity was significantly increased after cerebral ischemia–reperfusion, which decreased HDAC4 and HDAC5 expression and promoted apoptosis, at least to some extent, through the HMGB1 signaling pathway." (PMID 38740617, 2025). "Several evidences suggest that excess inflammation from the brain HMGB1/TLR4 axis activation is strongly contributes to traumatic brain injury and cerebral ischemia reperfusion injury." (PMID 37132060, 2023). "Our findings emphasize the crucial involvement of HMGB1 and RAGE in mediating cerebral ischemia-induced damage in the M1 region of the cerebral cortex." (PMID 37829255, 2023). "Since LPS is a canonical ligand that activates TLR4, we investigated the spatial distribution of HMGB1, an endogenous ligand of TLR4 released by damaged cells, after cerebral ischemia." (PMID 38082331, 2023). "In the MCAO-induced cerebral ischemia rat model, TMP administration significantly inhibited neutrophil migration and suppressed the activities of HMGB1 and TLR4." (PMID 36133805, 2022). "In our recent study, we presented evidence that celastrol directly bound to HMGB1 to inactivate it, up-regulated HSP70 and down-regulated NF-κB expression to play a neuroprotective effect in cerebral ischemia-reperfusion (I/R) injury in vitro and in vivo." (PMID 35656110, 2022). "Celastrol directly bound to HMGB1 to inactivate it, up-regulated HSP70 and down-regulated NF-κB expression to play neuroprotective effect in cerebral ischemia reperfusion injury in vitro and in vivo." (PMID 35656110, 2022). "Experimental and clinical studies have demonstrated the role of DAMPs (e.g., HMGB1 and Prxs) in TLR4-activated neuroinflammation after brain ischemia and hemorrhage." (PMID 34162400, 2021). "However, the role of HMGB1 in cerebral ischemia is complex and remains unclear." (PMID 33384585, 2020). "After cerebral ischemia, lncRNA-MIAT has proved to regulate the expression of HMGB1 (high-mobility group box 1) in cerebral microvascular endothelial cell (CMEC) injury by competing for miR-204-5p." (PMID 32605220, 2020). "This provides evidence for the functional role of HMGB1 and RAGE in a mouse model of cerebral ischemia." (PMID 33384585, 2020). "In an in vitro trial, HMGB1 worsens excitotoxic and ischemic neuronal death and HMGB is abundantly expressed in the brain and released during cerebral ischemia." (PMID 32994992, 2020). "A recent study reported that HMGB1, as an extracellular inflammatory cytokine, aggravates inflammatory damage to the BBB destruction during brain ischemia/reperfusion." (PMID 33384585, 2020).
Cerebral ischemia (continued). "In experimental animal models of cerebral ischemia–reperfusion injury (IRI) and in ischemic stroke patients, HMGB1 levels in the cerebral spinal fluid (CSF) and serum are significantly increased." (PMID 31001089, 2019). "However, in the late phase after neural ischemia, HMGB1 may enhance angiogenesis resulting in tissue remodeling by endothelial activation and sprouting, and it may promote neurovascular repair by activating endothelial progenitor cells after cerebral ischemia." (PMID 31123914, 2019). "UA was initially described that modulated potentially of HMGB1/TLR4/NFκB-mediated inflammation and ameliorated cerebral ischemia and reperfusion injury in the present study." (PMID 29867706, 2018). "We tested the role of HMGB1 in BBB disruption by complement activation in mouse brain ischemia and reperfusion experiments, by inducing MCAO injury and then monitoring the release of HMGB1 from brain parenchymal cells." (PMID 29696019, 2018). "Studies conducted by us and others revealed that the binding of extracellular HMGB1 to pattern recognition receptors of microglia could induce a significant elevation of cytokines expression, thereby eliciting inflammatory responses during brain ischemia/reperfusion." (PMID 30139371, 2018). "As a result, telmisartan shows its cerebroprotective effect, which inhibits the inflammatory reactions after cerebral ischemia, in a PPAR-γ-dependent manner, targeting HMGB1 expression and secretion." (PMID 27563308, 2016). "High mobility group box 1 (HMGB1) and nucleotide DAMPs such as adenosinetriphosphate (ATP) are released during cerebral ischemia." (PMID 25374510, 2014). "Previous studies align with our findings, indicating that glycyrrhizin modulates inflammation, oxidative stress, and related processes via the HMGB1/TLR4/NF-κB signaling pathway, benefiting neurological disorders such as cerebral ischemia, cognitive impairment, and neurotoxicity." (PMID 39834818, 2024). "For example, in a mouse model of focal cerebral ischemia-reperfusion injury, NLRP3 inflammasome inactivation was mediated by inhibition of the TLR4/NF-κB signaling pathway, which resulted in HMGB1 downregulation, consequently alleviating brain damage in ischemic stroke." (PMID 33384585, 2020). "At present, although a pivotal role of HMGB1 in cerebral ischemia is widely accepted, the specific mechanisms are not yet fully understood." (PMID 31001089, 2019). "HMGB1 is a nuclear DNA-binding protein and an important DAMP, which activates TLR2/4 and RAGEs signaling following rapid translocation to the cytoplasm or release from dying cells after cerebral ischemia." (PMID 31547018, 2019). "The addition of HMGB-1 in cultured glia and endothelial cells has further been shown to increase the level of TNF-α and ICAM-1, respectively, while in the MCAO model, the release of HMGB-1 from neurons at the earliest onset of brain ischemia was demonstrated." (PMID 31223427, 2019). "HMGB1 may also trigger MMP9 upregulation in neurons and astrocytes in mouse brains after cerebral ischemia." (PMID 28348451, 2017). "Interestingly, Hu and co-workers investigated the HMGB1-RAGE pathway in diabetic rats, showing its increase in brain ischemia together with a decreased functional outcome." (PMID 27898011, 2016). "Reactive oxygen species and reactive nitrogen increase after reperfusion, facilitate the HMGB1 activation and release, and interact with HMGB1 downstream immune receptors such as TLR2/4 and RAGE, which is a crucial pathological mechanism to amplify cerebral ischemia–reperfusion injury." (PMID 38740617, 2025). "To overcome the shortcomings of GA delivery and to improve the efficacy of cerebral ischemia therapy, herein, we designed reactive oxygen species (ROS) responsive polymer-drug conjugate nanoparticles (DGA) to manipulate microglia polarization by suppressing the translocation of nuclear HMGB1." (PMID 35415314, 2023).
Cerebral ischemia (continued). "By inhibiting JAK2/STAT3 signaling pathway, curcumin reduces the expression of HMGB1 in brain tissue after cerebral ischemia and reduces the release of TNF‐α and other inflammatory factors after cerebral ischemia, which significantly reduce the inflammatory response after cerebral ischemia." (PMID 38156383, 2023). "As HMGB1 not only induce NETosis but is also a part of the extruded NETs, reciprocal regulation between HMGB1 and PAD4 may contribute to this aggravation cycle in cerebral ischemia." (PMID 32731558, 2020). "In the present study, we, therefore, investigate the hypothesis that RA plays a neuroprotective role through the abrogation of HMGB1 release and NF-κB activation triggered by tumor necrosis factor-α (TNF-α) and ameliorates diabetic rats with MCAO-induced cerebral ischemia/reperfusion injury." (PMID 23414442, 2013). "However, the effect of BCP on HMGB1 expression in cerebral ischemia has not been studied." (PMID 40128654, 2025). "Thus, further investigation is required on whether or not massive release of HMGB1 is involved in activation of the HPA axis and SNS or immunodepression after cerebral ischemia, thereby increasing vulnerability to infection." (PMID 29555931, 2018). "HMGB1-RAGE signaling pathway has been confirmed as a critical player after brain injury as its inhibition was shown to improve the systemic metabolic and behavioral consequences of brain ischemia and reduce mortality without affecting the size of brain lesions." (PMID 27898011, 2016).